IGKV1-16 (immunoglobulin kappa variable 1-16)
Description:
V region of the variable domain of immunoglobulin light chains that participates in the antigen recognition. Immunoglobulins, also known as antibodies, are membrane-bound or secreted glycoproteins produced by B lymphocytes. In the recognition phase of humoral immunity, the membrane-bound immunoglobulins serve as receptors which, upon binding of a specific antigen, trigger the clonal expansion and differentiation of B lymphocytes into immunoglobulins-secreting plasma cells. Secreted immunoglobulins mediate the effector phase of humoral immunity, which results in the elimination of bound antigens. The antigen binding site is formed by the variable domain of one heavy chain, together with that of its associated light chain. Thus, each immunoglobulin has two antigen binding sites with remarkable affinity for a particular antigen. The variable domains are assembled by a process called V-(D)-J rearrangement and can then be subjected to somatic hypermutations which, after exposure to antigen and selection, allow affinity maturation for a particular antigen.
Synonyms: IGKV116; L1
Tractability: Antibody: its Gene Ontology location is reachable by antibodies, with high confidence; UniProt places it where antibodies can reach, with medium confidence; UniProt predicts a signal peptide or a membrane-spanning region.
Gene: Immunoglobulin variable (V) gene on chromosome 2 (89,099,859 to 89,100,361, reverse strand). Ensembl gene ENSG00000240864.
Subcellular location: Secreted; Cell membrane
Pathways (Reactome):
Immune System: Antigen activates B Cell Receptor (BCR) leading to generation of second messengers; CD22 mediated BCR regulation; Classical antibody-mediated complement activation; FCERI mediated Ca+2 mobilization; FCERI mediated MAPK activation; FCERI mediated NF-kB activation; FCGR activation; Fc epsilon receptor (FCERI) signaling; Immunoregulatory interactions between a Lymphoid and a non-Lymphoid cell; Initial triggering of complement; Regulation of Complement cascade; Regulation of actin dynamics for phagocytic cup formation; Role of LAT2/NTAL/LAB on calcium mobilization; Role of phospholipids in phagocytosis
Disease: FCGR3A-mediated IL10 synthesis; FCGR3A-mediated phagocytosis; Potential therapeutics for SARS
Hemostasis: Cell surface interactions at the vascular wall
Vesicle-mediated transport: Scavenging of heme from plasma
Gene Ontology:
Molecular function: antigen binding
Biological process: immune response
Cellular component: extracellular region; immunoglobulin complex; plasma membrane
Homologues: Orthologues: mouse Igkv15-103 (75% identical). Paralogues in human: IGKV1D-16 (96% identical), IGKV1-12 (91% identical), IGKV1-17 (91% identical), IGKV1-9 (90% identical), IGKV1D-12 (90% identical), IGKV1D-17 (90% identical), IGKV1-27 (89% identical), IGKV1-39 (89% identical), IGKV1D-13 (89% identical), IGKV1D-39 (89% identical), IGKV1-6 (88% identical), IGKV1-5 (86% identical), and 81 more.